TOP2B (DNA topoisomerase II beta)
Diseases named in the same sentence as TOP2B in open-access papers (continued):
Sharing a sentence is not in itself a finding about the gene and the disease.
cancer (52 papers, 2012 to 2026). A tumor composed of atypical neoplastic, often pleomorphic cells that invade other tissues. "In contrast, TOP2β performs a key function in cardiotoxicity and cancer development caused by TOP2 poison because its degradation mediates TOP2 poison-induced DSBs." (PMID 38263255, 2024). "Cancer genome databases were assessed for potential DNA damaging alleles, and two of four mutants tested Top2β-V111I and Top2β-K646N exhibited elevated levels of DNA cleavage." (PMID 39408578, 2024). "In the case of TOP2A, targeting of the C-terminus would enable selective targeting of TOP2A while avoiding TOP2B, which is associated with some treatment-induced adverse events (i.e. toxic effects of cancer therapy)." (PMID 36699404, 2022). "Consequently, inhibition of TOP2β degradation by an MDM2 inhibitor causes cancer cells to be more susceptible to VP-16 by promoting cancer cell apoptosis." (PMID 38263255, 2024). "Therefore, it is yet unknown if the degradation of TOP2β caused by these anti-cancer medications contributes to the death of cancer cells." (PMID 38263255, 2024). "In view of the possibility that the breaks are caused by Top2, it is worth mentioning that in mammalian cells, promoter proximal Top2β, in addition to being implicated in transcriptional regulation, has been incriminated as a crucial player in chromosomal translocations leading to cancer." (PMID 30445637, 2018). "While their antitumor efficacy relies on topoisomerase IIα (Top2α) inhibition in cancer cells, they primarily target topoisomerase IIβ (Top2β) in cardiomyocytes." (PMID 40558647, 2025). "In contrast, our pipeline, even when presented with mixed information from both older and recent studies, correctly identified that CX-5461 targets TOP2B in cancer with high confidence." (PMID 40293950, 2025). "Biologically, MDM2 inactivation abrogates TOP2β degradation, stabilizes TOP2βcc, and subsequently increases the number of TOP2β-concealed DSBs, resulting in the rapid death of cancer cells via the apoptotic process." (PMID 38263255, 2024). "Inhibitors of the DNA topoisomerase 1 (TOP1) and 2 (TOP2A and TOP2B) have shown considerable potential as therapeutic agents against cancers, including HNSCC." (PMID 38920662, 2024). "In summation, these in vivo data corroborate the notion that the combination of MDM2 inhibitors and TOP2β poisons has excellent in vivo anti-cancer efficacy." (PMID 38263255, 2024). "Beyond their essential physiological activities, TOP2α and TOP2β are treatment targets for widely prescribed anti-cancer medications, particularly, TOP2 poisons, including etoposide, doxorubicin, and teniposide." (PMID 38263255, 2024). "Survival analysis showed that the CNVs of TOP2B in 13 cancer types, TOP3B in 7 cancer types, TOP2A in 6 cancer types, TOP1MT in 6 cancer types, TOP3A in 5 cancer types and TOP1 in 5 cancer types significantly correlated with overall prognosis." (PMID 36288358, 2022). "There are two isoforms of the Top2 enzyme: Top2α, which is found mostly in proliferating cells such as cancer cells, and Top2β, which is present predominantly in quiescent cells such as cardiomyocytes." (PMID 35965684, 2022). "Top2α is mostly expressed in cells with high proliferation rates such as cancer cells, whereas Top2β is expressed on quiescent cells such as myocardium." (PMID 34582653, 2021). "To explore the potential for a CX-5461 therapeutic window in cancer patients, we also assessed the expression of TOP2B in normal human tissues using data from the Genotype-Tissue Expression (GTEx) consortium." (PMID 34753908, 2021).
cancer (continued). "For instance, doxorubicin inhibits both Top2a and Top2b, inhibiting Top2a have an anti-cancer effect while inhibiting Top2b have a cardiac side effect." (PMID 34026868, 2021). "Whereas the median expression of TOP2A was 31.3% higher than the median in all other cancer cell lines in DepMap RNA-seq data (P = 2 × 10−3), the median expression of TOP2B was 87.1% higher (P = 1.3 × 10−7)." (PMID 34753908, 2021). "In this study, we revealed the precise mechanism by which TOP2 poisons induce TOP2β degradation and demonstrated that specifically blocking TOP2β degradation remarkably sensitizes cancer cells to VM-26 treatment." (PMID 32015321, 2020). "Biologically, we demonstrated that SCFβ-TrCP-mediated TOP2β degradation promotes cancer cell survival by promoting DNA damage signals that facilitate DNA repair, whereas blockage of this degradation promotes cell killing via enhancing apoptosis." (PMID 32015321, 2020). "Top2β is instead ubiquitously expressed at significant levels in normal tissues and cancers, however it is generally more expressed in proliferating cells and tumors." (PMID 30404148, 2018). "In a mouse model of skin melanoma induced by etoposide, the skin-specific deletion of Top2β gene has been shown to protect skin cells from cancer transformation." (PMID 30404148, 2018). "The role of TOP2B is still ambiguous, and there are only limited reports about the correlation between the expression level of TOP2B and prognosis of cancer patients." (PMID 28355294, 2017). "TOP1, TOP2A and TOP2B levels in several human cancers were reported to be higher than those of normal or benign tissues, which was in accordance to the results from Oncomine." (PMID 27315793, 2016). "The anticancer effects of doxorubicin are believed to occur through the inhibition of topoisomerase-II enzymes (Top2β and Top2α) and the subsequent blockage of DNA resealing during replication that eventually leads to cell death of cancer cells." (PMID 27142468, 2016). "Identifying the protein–protein and protein–DNA interactions of TOP2B is essential for understanding its roles in development, transcription, and cancer." (PMID 27582050, 2016). "Thus, the small molecules that inhibit TOP2β degradation would disrupt this feed-forward loop to reduce DNA damage response and repair for enhanced cancer cell killing." (PMID 32015321, 2020). "Exposure to anti-cancer drugs, especially those targeting DNA topoisomerases may change the expression pattern of Top2α and Top2β genes." (PMID 31791417, 2019). "Interestingly, pixantrone, a compound structurally-close to anthracyclines, has been shown to target more effectively Top2α than Top2β in living cancer cells." (PMID 30404148, 2018). "Reports on the level of Top2β expression in cancer are very limited." (PMID 27462186, 2016). "Given that Top2β is over-expressed in cancer stem cells, we also investigated whether Top2β depletion might influence differentiation possibly through modulation of herby relevant genes." (PMID 27462186, 2016). "Similarly, MVP and genes encoding for Type I and Type II topoisomerases, such as TOP1, TOP2A, and TOP2B—known to contribute to cancer chemoresistance—showed the same negative association pattern." (PMID 40806276, 2025). "Notably, the cytotoxic TOP2cc levels in cancer cells may also drop as a result of TOP2β degradation, which can then result in the establishment of treatment resistance." (PMID 38263255, 2024). "Currently, no data exist about the mitochondrial protein levels of Top2α, Top2β, and Top3β in cancer cells compared to other cell types, but as these topoisomerases participate in mtDNA replication and expression, they should influence the metabolism of cancer cells." (PMID 31027213, 2019). "Thus, therapy-related chromosomal translocations causing secondary cancers can be due to poison interference with Top2β rather than Top2α." (PMID 30404148, 2018).
cancer (continued). "Anthracyclines induce their potent anti-cancer effects primarily via TOP2A, but at the same time they induce a dose limiting cardiotoxicity through TOP2B." (PMID 40425539, 2025). "For instance, one study demonstrated that the in vitro anti-cancer activity of double strand breaks (DSB) of DOX was mediated by both topoisomerase II alpha (TOP2A) and topoisomerase II beta (TOP2B) isoforms in HTETOP fibrosarcoma cell line." (PMID 37927589, 2023). "This subsequently downregulates the mRNA and protein level of DNA Topoisomerase II beta (TOP2B) involved in inducing DNA double-stranded breaks, and accumulation of TOP II-mediated DNA damage contributes to cancer cell death." (PMID 36359829, 2022). "It is noted that ETOPOSIDE, which targets TOP2A and TOP2B, exists in most drug pairs that are synergistic on the CAOV3 cancer cell line." (PMID 33577560, 2021). "Human cells express TOP2A and TOP2B genes, among which TOP2A is essential for cancer cell division because it is expressed at the S and M phases of the cell cycle, and is required for DNA replication and chromosome segregation for mitosis." (PMID 33598437, 2020). "Since TOP2B is expressed and remains active during the G1 phase of the cell cycle in non-proliferating benign cells, TOP2 poisons cannot differentiate cancer cells from benign cells when introducing genotoxic effects." (PMID 33598437, 2020). "The depletion of TOP2B and TOP2A suggests an explanation for the reported DRZ interference with cancer response to anthracyclines and for DRZ side-effects." (PMID 25406834, 2014). "Similarly, if transcription-dependent, TOP2B mediated DSBs trigger t-AL translocations as suggested above, then harmful genotoxic effects may be minimized by employing anti-cancer regimens in which a transcriptional inhibitor precedes administration of a TOP2 poison." (PMID 22829791, 2012). "Top2β, but not Top2α, appears to play a main role in the increased cancer incidence in patient survivors." (PMID 30404148, 2018). "In contrast, to optimize the antitumor activity, current research efforts aim at the discovery of Top2α-specific poisons, which are expected to not induce cardiomyopathies and secondary cancers, likely due to the Top2β." (PMID 30404148, 2018). "The depletion of TOP2B and TOP2A in tumors may suggest an explanation for the reported DRZ interference with cancer response to anthracyclines." (PMID 25406834, 2014). "When querying GPT-4o directly during our study in October 2024 (version 2024-05-13) without any retrieved literature, the model incorrectly inferred that CX-5461 does not target TOP2B in cancer, likely due to outdated information within its internal knowledge base." (PMID 40293950, 2025). "We speculate that a separate, rather than combined, administration of ATRA and Dox could mitigate DIC, while not affecting Dox cytotoxicity in cancer cells where the role of RAR signalling in Top2β control may not be relevant or tight." (PMID 35577872, 2022). "The selective degradation of TOP2B could prevent ANT-induced damage to the cardiomyocyte genome due to poisoning by this isoform and subsequent DNA double-strand breaks while sparing the TOP2A isoform in cancer cells." (PMID 24116135, 2013). "In addition, in line with the effects of etoposide treatment, TOP2B silencing induced MET and downregulated STT3 and PD-L1 in spheres (left), resulting in reduced PD-1 binding (upper right) and sensitization of sphere cells to PBMC-mediated cancer cell killing in vitro (bottom right)." (PMID 29765039, 2018). "Collectively, these data demonstrate that topobexin inhibits TOP2B, which reduces anthracycline-induced DNA damage, apoptosis, and cell death in post-mitotic cardiomyocytes over a range of concentrations, but does not hinder the anticancer effect of DAU in HL-60 cancer cells." (PMID 40425539, 2025).
tumor (25 papers, 1996 to 2026). "In the absence of TOP2A-specific anthracyclines, TOP2B-selective catalytic inhibitors pose a unique opportunity to strategically prevent TOP2B poisoning in the heart while leaving TOP2A in tumours susceptible to anthracycline poisoning." (PMID 40425539, 2025). "As it is known that ATM is associated with the degradation of TOP2β, and induces tumor cells to exhibit resistance to VP-16." (PMID 36650267, 2023). "Tumours with amplified TOP2B had better event-free survival, whereas TOP2B deletion conferred poorer event-free survival." (PMID 32961800, 2020). "It is expected that the expression of wild type Top2α and Top2β decreases in chemotherapeutic resistant tumor cells." (PMID 31791417, 2019). "The DRZ-driven depletion of TOP2B is apparently transient, which would likely minimize any long-term effects deleterious to tumor cell survival." (PMID 25406834, 2014). "DRZ-driven depletion of TOP2B would be expected to reduce this damage and thereby the elimination of tumor cells." (PMID 25406834, 2014). "However, despite the anti-tumor activity, our mechanistic work raises the possibility of late-emerging adverse events when TOP2B is targeted, which needs to be further understood before this combination is applied in a pediatric patient cohort." (PMID 34753908, 2021). "We next assessed the expression of TOP2B across TCGA tumor samples." (PMID 34753908, 2021). "Thus, our study suggests a novel strategic drug combination of TOP2 poisons with an inhibitor targeting TOP2β degradation for maximal killing efficiency of tumor cells." (PMID 32015321, 2020). "The exact role of TOP2B in tumor was expected to be elucidated." (PMID 27315793, 2016). "However, it is unknown whether TOP2β degradation induced by these chemotherapeutic drugs contributes to the killing of tumor cells." (PMID 32015321, 2020). "Furthermore, Top2β has also been reported to be overexpressed in GBM tumor initiating cells." (PMID 30841565, 2019). "In contrast to post-mitotic cells such as cardiomyocytes, proliferating cells such as tumor cells express TOP2A or both isoforms rather than TOP2B alone." (PMID 25406834, 2014). "Although the anti-tumor effects of TOP2 poisons are usually attributed to TOP2A rather than TOP2B, the application of TOP2A level as a therapeutic predictor has been unsuccessful." (PMID 25406834, 2014). "Therefore, microsatellite analysis was performed in all tumor specimens using six couples of primers targeting the 17q21 amplicon, containing TOP2A and ERBB2 genes, and 3p24 and 20q12–q13.1 loci, containing respectively TOP2B and TOP1 genes." (PMID 24216996, 2013). "Inhibition of TOP2B, therefore, rather than inducing trans-differentiation from ADRN to MES, might select for the MES tumor component by specifically killing the ADRN tumor component." (PMID 37849756, 2023). "Unfortunately, we could not study the effects of the TOP2B-BRAF fusion on chromatin conformation, as tumor tissue from JPA_3 was not available for Hi-C." (PMID 36503484, 2022).
neurodevelopmental disorder (6 papers, 2015 to 2025). A behavioral and cognitive disorder with onset during the developmental period that involves impaired or aberrant development of intellectual, motor, or social functions. "Recently, several de novo missense TOP2B variants have been identified in patients with neurodevelopmental disorders (NDDs)." (PMID 40656194, 2025). "Mutations of TOP2B lead to neurodevelopmental disorder and diastolic dysfunction, which are phenotypically similar to when SMC5/6 components are mutated." (PMID 38203602, 2023). "Recently, a de novo missense TOP2B variant (c.187C>T) has been identified in an individual with neurodevelopmental disorder (NDD)." (PMID 31953910, 2020). "Our study points to potential mechanisms for Top2β involvement in neurodevelopmental disorders, not necessarily at the time of synapse formation but rather early in development as neuronal subtypes are being generated." (PMID 29379870, 2017).
infection (3 papers, 2020 to 2025). The state of being infected such as from the introduction of a foreign agent such as serum, vaccine, antigenic substance or organism. "Our analysis reveals that vaccinia redirects TOP2A and TOP2B to cytosolic sites of viral replication early during infection in a two-step process." (PMID 40557872, 2025). "These pulldowns also verified that TOP2B associates with DDX1, FAM98A, and RTCB, suggesting a potential role for this isoform in RNA metabolism during infection." (PMID 40557872, 2025). "To identify infection-specific partners, we performed GFP pull downs on infected cells expressing GFP-tagged TOP2A or TOP2B CTDs with mutated NLS, as these proteins are recruited to viral factories, but not nuclear DNA." (PMID 40557872, 2025). "Although the presence of TOP2A and TOP2B on cytosolic viral factories has been established, their specific roles during vaccinia replication and infection remain unexplored." (PMID 40557872, 2025). "The loss of TOP2B but not TOP2A also resulted in a decrease in dsRNA formation during infection, which is consistent with a reduction in AVG formation." (PMID 40557872, 2025). "Given that four of the identified TOP2B interaction partners play a role in RNA granule formation, we explored whether these proteins are components of AVGs during infection." (PMID 40557872, 2025). "Only a few host proteins were found to interact preferentially with TOP2B during infection." (PMID 40557872, 2025). "This was achieved with lentivirus infection of siRNA against Top2b." (PMID 33330654, 2020). "At 7 h post infection, TOP2A was located both, in the nucleus and at the viral factories, while TOP2B was completely recruited to viral factories." (PMID 40557872, 2025).
neurodegenerative disease (1 paper, 2019). A disorder of the central nervous system characterized by gradual and progressive loss of neural tissue and neurologic function. "Although Top2β-mediated DSBs are needed for functional NMDAR signaling, the misrepair of such DSBs is considered to promote neurodegenerative diseases and also carcinogenesis." (PMID 30841565, 2019). "However, it is worth mentioning that the risks of interfering with Top2β-mediated cleavage and rejoining as fundamental processes for regulated transcription are difficult to estimate, since the misrepair of such DSBs is considered to promote neurodegenerative diseases and carcinogenesis." (PMID 30841565, 2019).
TOP2B also shares sentences with these, for which no sentence is quoted: developmental delay (4 papers); Myocardial fibrosis (3); Immunodeficiency (2); microcephaly (2); Parkinson disease (2); ablepharon macrostomia syndrome (1); acute lymphoblastic leukemia (1); Anxiety (1); Arrhythmia (1); atherosclerosis (1); Atrophy (1); bladder carcinoma in situ (1); cardiovascular disease (1); chronic pancreatitis (1); Cockayne Syndrome B (1); colorectal cancer (1); congestive heart failure (1); coronary artery disease (1); diabetic retinopathy (1); gastric cancer (1); hematological cancer (1); hepatocellular carcinoma (1); HIV-1 infection (1); infantile epileptic spasms syndrome (1); liver cancer (1); lung adenocarcinoma (1); lung carcinoid tumor (1); melanoma (1); myocarditis (1); non-Hodgkin lymphoma (1).
A further 9 diseases each share a sentence with TOP2B in 1 paper.